NLRP1 (NLR family pyrin domain containing 1)
Diseases named in the same sentence as NLRP1 in open-access papers (continued):
Sharing a sentence is not in itself a finding about the gene and the disease.
tumor (continued). "Immunohistochemistry indicated that CASP4 was expressed at high levels in tumor tissues but weakly expressed in adjacent normal tissues, and the difference in NLRP1 expression between tumor and adjacent normal tissues was opposite to that of CASP4." (PMID 35633405, 2022). "The expression levels of NLRP1/NLRP3 were significantly correlated with tumor stage and degree in patients with GC." (PMID 36541912, 2022). "5-aza-2-deoxycytidine (DAC) restores the expression of NALP1 and inhibits tumor proliferation by inducing NLRP1-mediated caspase-1-dependent pyroptosis." (PMID 36262473, 2022). "Because the roles of NLRP1/NLRP3 in immune invasion in GC are affected by various cytokines in the tumor microenvironment, further in vitro and in vivo studies are needed to elucidate the related mechanisms." (PMID 36541912, 2022). "In contrast, the NLRP1 inflammasome pathway is restrained in established cSCCs, suggesting that, at this stage, the protein complex has a tumor suppressor role." (PMID 36293159, 2022). "Nevertheless, the expression of not only ASC but of all inflammasome proteins is suppressed in established cSCC, suggesting a tumor suppressor role of the NLRP1 inflammasome pathway during cSCCs progression." (PMID 36293159, 2022). "Compounds that inhibit the DPP4 enzyme family, such as talabostat and ARI-4175, can mediate tumour regression by immune-mediated mechanisms that are believed to include NLRP1 activation." (PMID 34771657, 2021). "Decreased NLRP1 expression led to worsening of clinical features (pathological stage of tumor, lymph node metastasis status, primary tumor status and prognosis)." (PMID 33658393, 2021). "Hyper-activation NLRP1 inflammasome led to decreasing of tumor cells’ death and increased inflammatory microenvironment driven by IL-18 and IL-1β secretion, which has been proposed as a common mechanism of NLRP1 serving an instigator." (PMID 33658393, 2021). "We recommend strongly that researchers in the field of tumor immunology conduct further research on NLRP1 in LUAD to gradually elaborate the biological role of NLRP1 in the immune microenvironment and prognosis of LUAD patients." (PMID 33658393, 2021). "The authors demonstrated that the inhibitory effect of EGCG on tumor proliferation was abolished by silencing NLRP1, suggesting the role of inflammasomes in the tumor-inhibitory effect of EGCG in HMC." (PMID 32650482, 2020). "NLRP1 mRNA expression levels were significantly upregulated in the tumor cells from TMZ-treated animals compared to those from control mice." (PMID 32899791, 2020). "Spinal cord NLRP1 inflammasome-mediated inflammatory response contributes to dry skin-induced chronic itch by TRPV1 channel, and it is also involved in age and sex differences of chronic itch." (PMID 32312281, 2020). "Recent studies showing that the serine dipeptidases DPP8/9 inhibit activation of NLRP1 has put renewed interest in past studies on inhibitors of these peptidases (like talabostat) as anti‐tumor agents." (PMID 32027447, 2020). "Several genes encoding core inflammasome components were all significantly expressed at higher levels in ACP tumours compared with control tissues, including NLRP1 (6.4-fold), NLRP3 (4.8-fold), NLRC4 (4.8-fold), CASP1 (5-fold) and PYCARD (4-fold) [Suppl." (PMID 29541918, 2018). "The inhibitory effect of EGCG on tumor proliferation was eliminated by silencing NLRP1, signifying a key role of inflammasomes in the tumor-inhibitory effect of EGCG in human melanoma cells." (PMID 30585192, 2018). "The knockdown of NLRP-1 resulted in reduced IL-1β production and secretion, which led to the reduction of tumor proliferation in vivo and in vitro." (PMID 30149677, 2018). "Whereas, NLRP1-transfected cells exhibited unique irregular shapes and distinguishing spread features, suggesting that NLRP1 more likely induced tumor epithelial-mesenchymal transition (EMT)." (PMID 29214170, 2017).
tumor (continued). "In sum, these results obtained from the TCGA database indicate that across tumor stages, NLRP1, NLRP3, NLRC3, NLRC4 and AIM2 expression in CRC tissues was significantly less than healthy controls." (PMID 26378020, 2015). "In a separate study, NLRP1/NLRP3 expression was linked to poor overall survival, advanced stage, the development of lymph node metastases, and the infiltration of immune cells in the tumour microenvironment." (PMID 41148809, 2025). "Using cBioPortal, we examined the genetic alterations of NLRP1 across 32 TCGA tumor types." (PMID 40237399, 2025). "The expression status of NLRP1 in various tumor types from different sources." (PMID 40237399, 2025). "Our finding of a positive regulation of NLRP1 expression by miR-34a raises the possibility that pharmacological treatment of cSCC patients with mimics of the miR might increase anti-tumor immunity and other tumor suppressive effects downstream of NLRP1." (PMID 40593496, 2025). "Additionally, our study revealed statistically significant associations between the transcriptional level of NLRP1 and the pathological stage of BLCA, LUAD, PAAD, and READ tumor tissues." (PMID 40237399, 2025). "This inverse relationship indicates that NLRP1 may play a potentially suppressive role in the recruitment or propagation of CAFs within the tumor microenvironment." (PMID 40237399, 2025). "NLRP1 expression is significantly different in most tumour immune subtypes." (PMID 39318060, 2024). "Overexpression of NLRP1 inhibited tumor growth in vitro and in vivo." (PMID 39258674, 2024). "It is therefore hypothesized that NLRP1 may serve as an effective clinical biomarker and have a substantial impact on both tumour immunity and metabolism." (PMID 39318060, 2024). "The different impacts of NLRP1 on the prognosis of various tumour subtypes may be explained by the variable expression of NLRP1 in distinct subtypes of tumours." (PMID 39318060, 2024). "It is worthwhile to investigate the effect of NLRP1 on tumour immunology and metabolism since it may have a variety of essential functions in various types of tumours." (PMID 39318060, 2024). "By examining the relationship between NLRP1 levels and the immune environment, this study aims to provide valuable insights that could inform the development of immunotherapy across a range of tumours, offering novel guidance for cancer treatment." (PMID 39318060, 2024). "Downregulation of NLRP1 reduced tumour metabolic activity in LUAD." (PMID 39318060, 2024). "By influencing the metabolic environment, NLRP1 can regulate tumour progression." (PMID 39318060, 2024). "NLRP1 plays a significant role in tumour immunity as a critical gene of cell pyroptosis." (PMID 39318060, 2024). "Additionally, a notable increase in tumor marker gene expression was observed in cells with functional NLRP1 and NLRP3 following UV radiation, whereas silencing these inflammasome genes altered the expression profiles of these markers." (PMID 39839625, 2024). "Thus, we used the diverse immunological signatures to examine the relationship between tumour NLRP1 inflammasome and tumour immunity." (PMID 39318060, 2024). "Moreover, we report that NLRP1 expression is significantly different in various tumours for the first time and the variations are correlated with immune cell infiltration, immune subtypes and immune‐related pathways." (PMID 39318060, 2024). "Therefore, agents inhibiting mRNA or protein expression of inflammasome components reduce NLRP1 activation and the inflammatory response in the tumor microenvironment." (PMID 38990306, 2024). "Interestingly, high NLRP1 expression inversely correlated with tumour stemness while positively correlating with tumour immune infiltration in various cancers including LUAD and PAAD." (PMID 39318060, 2024). "Notably, NLRP1 exhibits distinct characteristics in different tumours, suggesting its abnormal expression influences on tumour metabolism and immune response within the tumour microenvironment." (PMID 39318060, 2024).
tumor (continued). "It was found that NLRP1 might promote tumor growth through activation of inflammasomes and inhibition of apoptosis in metastatic melanoma." (PMID 39258674, 2024). "Remarkably, the NLRP1 overexpression group displayed a significantly reduced tumor burden." (PMID 39258674, 2024). "The antigens CARD8, NAIP, NLRP1, and NLRP3, which are associated with tumor pyroptosis, could be candidate molecules for LUAD mRNA vaccine development." (PMID 38166691, 2024). "Moreover, the relationship between NLRP1 mutations and expression level with patient prognosis, as well as NLRP1 and tumour immunity, was unclear." (PMID 39318060, 2024). "The study suggests that the different prognosis of NLRP1 in different tumours may be related to its variable expression in different cells." (PMID 39318060, 2024). "In addition, NLRP1 has been positively correlated with the degree of infiltration of tumor-infiltrating immune cells." (PMID 37497237, 2023). "NLRP1/NLRP3 expression was varied among datasets for the same tumor type." (PMID 36541912, 2022). "Consequently, we analyzed NLRP1/NLRP3 expression in different tumor types based on TCGA RNA-seq data." (PMID 36541912, 2022). "Gene sets of tumor immune-related enriched in NLRP1/NLRP3 high expression Group." (PMID 36541912, 2022). "Previous studies have shown that NLRP1 is considered a tumor suppressor gene." (PMID 35633405, 2022). "NLRP1 expression showed a negative association with drug sensitivity, proving its tumour promotional role." (PMID 35246158, 2022). "However, the mechanisms of how NLRP1 exerts its tumor suppression effect in the immune system need further research." (PMID 36119049, 2022). "Moreover, the knockdown of NLR family pyrin domain containing 1 (NLRP1) reduces their tumour-promoter properties, both in vivo and in vitro." (PMID 35334544, 2022). "Compared with the human immortalized normal ductal epithelial cell line, the expression of NLRP1 and TNF in tumor cell lines was remarkably higher, the expression of NLRP1 was the highest in BX cell lines, and the expression of TNF was the highest in PANC-1 cell lines." (PMID 35785176, 2022). "In contrast, chronic NLRP1 activation is responsible for persistent inflammation, which can be considered as tumor promoter in the skin, which might be mediated by inflammation-associated ROS and IL-1β." (PMID 36293159, 2022). "This might be due to the link between inflammatory and apoptotic caspases, as NLRP1 was described both as an inflammasome forming protein and also as a key mediator of apoptosis in cancer cells, similar to the tumor suppressor ASC." (PMID 34777694, 2021). "NLRP1 inflammasomes activate the NF-κB pathway, a known tumor promoter." (PMID 32899791, 2020). "This scenario could explain the tumor-promoting role of NLRP1, not only in the targeted therapy resistance observed in this study, but also in the chemotherapy resistance we observed previously." (PMID 33396632, 2020). "However, tumor volume and weight were greater in the animals injected with NLRP1 transfected MCF-7 cells." (PMID 29214170, 2017). "Maybe just like NLRP3, we speculate that NLRP1 becomes activated in tumor microenvironment by inflammatory factor, endogenous ATP, cell damage, HMGB1, or potassium efflux." (PMID 29214170, 2017). "The infiltration of CAFs may further modulate the role of NLRP1 in the tumor microenvironment." (PMID 40237399, 2025). "It seemed that the effect of tumor inhibition was more pronounced in NLRP1-overexpressing PC-9 cells compared to H1299 cells, which might be partially due to their different basal expression of NLRP1." (PMID 39258674, 2024). "Thus, NLRP1 may prefer to reprogram tumour energy metabolism, thereby suppress the progression of LUAD." (PMID 39318060, 2024).
tumor (continued). "In this study, NLRP1 is shown to be inversely connected with the tumour stemness index of RNAss, suggesting that high expression of NLRP1 can be accompanied by a decrease in tumour metastasis, as well as a comparative reduction of the drug resistance and self‐renewal ability of tumours." (PMID 39318060, 2024). "Thus, the relationship between NLRP1 and tumours has come to the foreground." (PMID 39318060, 2024). "In addition, NLRP1/NLRP3 may also be involved in several important tumor-related pathways, such as MAPK and JAK-STAT pathways." (PMID 36541912, 2022). "The deregulation of NLRP1 inflammasome could contribute to the formation of the pro-tumor micro-environment both influencing the transformation of the lung tissue cells and/or inducing high levels of IL-1ß that contribute to growth and metastatic spread in experimental and human cancers." (PMID 23031505, 2012). "This study identifies NLRP1 and NLRP3 inflammasomes as potential biomarkers and therapeutic targets in NMSC, linking their altered expression to tumour progression and recurrence." (PMID 42222687, 2026). "Our analysis revealed decreased expression of NLRP1 in BLCA, BRCA, KICH, LUAD, LUSC, PRAD, and UCEC tumor tissues compared to normal tissues." (PMID 40237399, 2025). "Our analysis of gene expression unveiled a decrease in NLRP1 levels in BLCA, BRCA, KICH, LUAD, LUSC, PRAD, and UCEC tumor tissues compared to normal ones." (PMID 40237399, 2025). "Our findings indicate a consistent downregulation of the NLRP1 gene in tumor tissues of BLCA, BRCA, KICH, LUAD, LUSC, PRAD, and UCEC, while notable overexpression of NLRP1 was observed specifically in CHOL and HNSC." (PMID 40237399, 2025). "In summary, our findings revealed a novel pathway regulating suppression of the inflammasome sensor NLRP1 in SCC cells by p62, which occurs at the mRNA level and is mediated by miRs, including the tumor suppressive miR-34a-5p." (PMID 40593496, 2025). "For Triple‐I tumors, in addition to IFNG mediated cytotoxic T‐cell tumor killing involving genes, like GZMB, high AIM2 along with NLRP1 expression support a role of pyroptosis via inflammasomes." (PMID 40492347, 2025). "The findings demonstrated high expression of AIM2 in tumor tissues and low expression of CASP1, NLRP 3, and NLRP1 in tumor tissues." (PMID 40026444, 2025). "In this study, we also demonstrated that NLRP1 expression was significantly decreased in LUAD, and its downregulation promoted tumor progression." (PMID 39258674, 2024). "NALP1 is part of the NLRP1 inflammasome, which can induce the maturation and secretion of IL-1β, activate inflammatory responses, and promote tumor growth and spread." (PMID 38780447, 2024). "Another interesting finding in our results is that the four prognostic PRGs (BAK1, CYCS, HMGB1, and NLRP1) were significantly correlated with immune cell infiltration, which further confirmed that pyroptosis in immune cells might participate in regulating the tumour microenvironment." (PMID 37337018, 2023). "As previously observed in mRNA expression level, CASP4, GPX4, IL18, NLRP1, and IRF1 were upregulated in tumor samples, whereas PLCG1 was downregulated." (PMID 35000541, 2022). "The analysis demonstrated that in comparison with normal brain tissues, 20 pyroptosis-related genes were upregulated in the tumor (e.g. CASP1 and CASP3), and 11 pyroptosis-related genes were significantly downregulated in the tumor (e.g. GSDMB and NLRP1)." (PMID 35274175, 2022). "Homogeneously, our findings evidenced that NLRP1 and NLRP3 were significantly downregulated in tumor compared to normal lung tissues." (PMID 35866781, 2022). "The relationships of NLRP1/NLRP3 expression and tumor-infiltrating immune cells/marker genes were assessed using the TIMER database." (PMID 36541912, 2022).
tumor (continued). "NLRP1/NLRP3 and immune checkpoint gene correlations were verified by single-gene co-expression analyses, and tumor immune-related pathways involving NLRP1/NLRP3 were analyzed using gene set enrichment analysis (GSEA)." (PMID 36541912, 2022). "We first assessed the immunofluorescence intensity of selected inflammasome components (NLRP1, NLRP3, NLRP6, AIM2, ASC, Caspase-1, IL-1β and IL-18) in tumor cells compared to normal epithelial cells, for each patient." (PMID 33255437, 2020). "NLRP1 and NLRP3 inflammasomes are promising tumour markers for NMSC." (PMID 42222687, 2026). "This literature review shall further examine and summarize whether NLRP1 and NLRP3 inflammasomes could be potential tumour markers of NMSC." (PMID 42222687, 2026). "This suggests that development of cSCCs is supported by NLRP1 activation at early stages of tumor development, but has negative consequences for established cSCCs." (PMID 40593496, 2025). "In previous studies, the research on NLRP1 was restricted to specific tumours and did not consider tumour immunity or immune metabolism." (PMID 39318060, 2024). "Until now, only a limited number of studies have investigated the role and function of NLRP1 in cancer studies, most of which are limited to a single type of cancer and have not studied the relationship between NLRP1 and tumour immunity or metabolism." (PMID 39318060, 2024). "The function of inflammasomes, particularly NLRP1 in tumour metabolism, has not yet been investigated." (PMID 39318060, 2024). "Among that, 33 PRGs were upregulated, while NLRP1 and PJVK was downregulated in tumor samples." (PMID 35000541, 2022). "Interaction network results revealed that BAK1, NLRP1, CHMP7, and RIPK1 genes could interact with immune factors, including TNF-α, suggesting their influence on the immune microenvironment of the HNSCC tumor." (PMID 36246601, 2022). "Multiple inflammasomes, including NLRP3, NLRC4, NLRP1, and AIM2, may inhibit tumor initiation by influencing innate and adaptive immunity, apoptosis, and differentiation." (PMID 36437954, 2022). "Moreover, with the expression level of NLRP1 decreasing, the progression of LUAD got worsen, which specifically reflected on the advanced clinical characteristics of tumor pathological stages, lymph node metastasis status, and primary tumor status." (PMID 33658393, 2021). "Furthermore, our statistical analysis examining the significance of the differences observed between NLRP1 transcript levels and the pathological stage of various cancers revealed significant relationships solely in BLCA, LUAD, PAAD, and READ tumor tissues (p‐value < 0.05)." (PMID 40237399, 2025). "Unlike NLRP3, NLRP1 is positively correlated with high degree of immune cells infiltration that enhances the immune microenvironment of tumours, thereby improving patient prognosis in tumours, such as in LUAD." (PMID 39318060, 2024). "However, in tumours, there is a significant negative correlation between NLRP1 expression and genes involved in amino acid metabolism." (PMID 39318060, 2024). "Similarly, mutations in NLRP1, ALK, and MAP3K1 were frequent among non-responders and tumor mutation count was significantly reduced in post-treatment samples." (PMID 36376989, 2022). "Due to the important role of anti-tumor immunity in controlling development of cutaneous SCCs, it is tempting to speculate that SCC cells in vivo might profit from attenuation of anti-tumor immune responses downstream of NLRP1 inflammasome suppression." (PMID 36581625, 2022). "Furthermore, NLRP1/NLRP3 may be involved in macrophage polarization, T-cell exhaustion, Tregs, immune checkpoint regulation, and other tumor immune regulatory processes." (PMID 36541912, 2022). "NLRP1 and NLRP3 might be involved in the same tumor immune-related pathways." (PMID 36541912, 2022). "Therefore, NLRP1/NLRP3 may regulate immune infiltration in GC through these immune- and tumor-related pathways." (PMID 36541912, 2022).